TERT (telomerase reverse transcriptase)
Diseases named in the same sentence as TERT in open-access papers (continued):
Sharing a sentence is not in itself a finding about the gene and the disease.
thyroid cancer (continued). "An association between the TERT –245T>C polymorphism and BRAF mutation was investigated, but not found, in a study on differentiated thyroid cancer, showing that BRAF mutation was not correlated to TERT –245T>C polymorphism as an additional prognostic factor." (PMID 29464027, 2018). "Unfortunately, five single-arm and three uncontrolled retrospective studies on MAPK inhibition of metastatic RAI-resistant thyroid cancer with BRAF, RAS, or no detected driver mutation for RAI re-sensitization do not provide any information regarding TERT mutation analysis." (PMID 38642578, 2024). "A false-positive TERT result could lead to overtreatment, while a false-negative test may not alert clinicians to a worse prognosis and thyroid cancer outcome." (PMID 38441247, 2024). "In addition, we observe that partial inhibition of MAPK, a central pathway in thyroid cancer transformation, is more effective at suppressing TERT transcription in the absence of TPMs." (PMID 35053525, 2022). "In conclusion, TERT promoter mutated FTCs may exhibit a specific miRNA pattern that in part regulates key cancer pathways, an observation that may support non-canonical TERT functions in thyroid cancer." (PMID 34676499, 2021). "Interestingly, CTCF was observed not to bind to TERT in normal thyroid tissue despite the presence of methylation, while thyroid cancer cell lines exhibited both partial methylation and CTCF binding." (PMID 33329574, 2020). "While all of these regulatory strategies are altered in thyroid cancer, and may play a significant role in TERT activation, these altered regulatory mechanisms have not yet been leveraged clinically." (PMID 32849278, 2020). "The half-life period of TERT was not affected by FOXD2-AS1 in thyroid cancer cells." (PMID 31024447, 2019). "Furthermore, we observed that the MAPK blockade was more efficient at suppressing TERT transcription in cells without TPMs, suggesting that a switch in TERT-mutant control might operate in thyroid cancers carrying TPMs." (PMID 35053525, 2022). "Our results found that silencing FOXD2-AS1 reduced the protein, but not the mRNA, expression levels of TERT in thyroid cancer cells, suggesting that FOXD2-AS1 regulates TERT expression at post-transcriptional level." (PMID 31024447, 2019). "Considering the known role of MAPK signaling in regulating wild-type TERT expression, we sought to explore the effect of MAPK blockade in thyroid cancer cells with or without TPMs and to assess whether it cooperates with ETS to control TERT transcription." (PMID 35053525, 2022). "Regarding thyroid cancer types, we observed a trend, although not statistically significant, where follicular thyroid carcinoma (FTC) had a higher AF at 30.8% compared to papillary thyroid carcinoma (PTC) with an AF of 22.5%, regardless of the presence of TERT (p = 0.104)." (PMID 40940948, 2025).
breast carcinoma (153 papers, 2005 to 2025). "Although TERT promoter mutations have been described in only 0.9% of breast cancers, in studies by Gerald, Zhong, Krings, and Chen, 15 of 17 cases (88%) harbored TERT promoter alterations." (PMID 41488090, 2025). "Following PST, many cases showed increased cytoplasmic TERT expression in breast cancer cells, which was associated with resistance." (PMID 39871386, 2025). "In breast cancer, TERT promoter mutations are exceptionally rare, occurring in only 0.9% of tumor tissues." (PMID 39871386, 2025). "Though TERT has been primarily regarded as an ER- gene since several GWAS variants in TERT have been associated with ER- BC, our study shown that the predicted expression of TERT was also significantly associated with ER + breast cancer risk." (PMID 38515142, 2024). "Eventually, 74 potential pleiotropic genes werefound.Notably, the gene TERT was significantly associated with both breast cancer andovarian cancer detected by the two tests." (PMID 38626574, 2024). "A number of studies have suggested that the rs10069690 polymorphism, located in intron 4 of the TERT gene, is a risk factor for several types of cancer, including breast cancer." (PMID 36768147, 2023). "This study aimed at analysis of the association of rs10069690 genotype and TERT expression with the risk, age at onset, prognosis, and clinically and molecularly relevant subtypes of breast cancer." (PMID 36768147, 2023). "Different studies have suggested that the rs10069690 variant in the TERT gene is a risk factor for several types of cancer, including breast cancer and ovarian, lung, and thyroid cancer." (PMID 36768147, 2023). "In solid tumours, such as lung cancer and breast cancer, the presence of mutations in the TERT promoter is closely related to poor prognosis." (PMID 35251214, 2022). "Hashemi and co-authors found that TERT rs2736098 polymorphism genotype increased the risk of breast cancer (OR 1.80 (1.12–2.88), p = 0.017, HP versus AA; OR 1.80 (1.06–3.06), p = 0,033, GG vs. AA; GS = 1.87 (1.19–2.94), p = 0.006, AG + GG versus AA)." (PMID 35892421, 2022). "Further studies are required to confirm the frequency of TERT promoter mutations in this rare type of breast cancer." (PMID 33021035, 2021). "TERT promoter hotspot mutations and gene amplification are rare in common forms of breast cancer, but present in a subset of phyllodes tumors." (PMID 33863915, 2021). "Associations between TERT and β-catenin have been reported in diverse cancer types, including gastrointestinal cancers, medulloblastoma, breast cancer, and osteosarcoma." (PMID 34439356, 2021). "TERT copy number amplification has been observed in various cancers including skin, thyroid, and breast cancer where it was found to be associated with increased TERT expression and was positively correlated with worse clinical outcomes." (PMID 32674474, 2020). "Given the rarity of TERT promoter mutations, further studies are needed to confirm their prognostic significance in breast cancer cases." (PMID 29222734, 2018). "This is the first detailed report regarding TERT promoter mutations in human breast cancer, and we identified TERT promoter mutations in three (0.9%) of 319 samples." (PMID 29222734, 2018). "In breast cancer, only limited data are available concerning the incidence of mutations and SNP in the TERT promoter, TERT gains and their relationship with TERT upregulation and patient prognosis." (PMID 29100407, 2017). "Another previous study found that the variant allele at TERT rs4246742 was inversely associated with breast cancer risk, while positive associations were found for rs10069690 (OR = 1.13), rs2242652 (OR = 1.51), and rs2853676 (OR 1.23)." (PMID 28060765, 2017).
breast carcinoma (continued). "Particularly aggressive breast cancers were characterized by an association of TERT gains with MYC overexpression." (PMID 29100407, 2017). "Only the ESR1 (rs2046210), TERT (rs2242652) and two 19p13.1 (rs8170; rs56069439) loci had genome-wide significant associations with breast cancer risk for BRCA1 mutation carriers alone." (PMID 27117709, 2016). "Region 5p15.33, showing excess African ancestry associations with ER- breast cancer, contains the TERT gene, which harbors a well-known ER- specific breast cancer associated variant, rs10069690." (PMID 27708667, 2016). "Others researchs have implicated that the TERT gene in regulation of breast cancer telomerase activity." (PMID 26383170, 2015). "Variants in or near the known breast cancer susceptibility loci TERT, ESR1 and 19p13.11 showed strong associations (P <10−6) with at least one of the categories in all subtype analyses in BRCA1 carriers." (PMID 25919761, 2014). "The minor allele of rs2736098 located in TERT gene was associated (p-valuecor of 9.30E-04) with a decreased risk of breast cancer." (PMID 24171766, 2013). "Noteworthy is that the minor allele of rs2736098, the synonymous polymorphism in TERT gene, was associated with a decreased risk of overall breast cancer, which by now was observed only among women in Poland." (PMID 24171766, 2013). "We demonstrate that the minor alleles at rs2736109, and at an additional TERT promoter SNP, rs2736108, are associated with decreased breast cancer risk, and that the combination of both SNPs substantially reduces TERT promoter activity." (PMID 21949822, 2011). "The associations of TERT −1381C>T, −244C>T, Ex2-659G>A and the corresponding haplotype in individuals with a family history of breast cancer are intriguing and warrant follow-up in independent studies." (PMID 17848914, 2007). "Case–control analyses suggested inverse associations between homozygous variants of TERT and breast cancer risk at two SNP sites, TERT-1654A>G (OR 0.85, 95% CI 0.72–1.02) and TERT Ex2-659G>A (A305A) (OR 0.76, 95% CI 0.58–1.00)." (PMID 17848914, 2007). "Intriguing associations with variants in TERT among women with a family history of breast cancer warrant follow-up in independent studies." (PMID 17848914, 2007). "Additionally, the TERT locus was previouslyreported to be associated with breast cancer and ovarian cancer." (PMID 38626574, 2024). "Furthermore, in a study involving 28 metaplastic breast cancers, nearly half of the tumors with spindle/squamous differentiation were enriched for TERT promoter mutations." (PMID 37612721, 2023). "We found that a moderate SMF (~150 mT) accelerated cell proliferation but inhibited breast cancer cell migration and shortened telomere length, which was associated with decreased telomerase activity and expression of TERT, as well as corresponding upregulation of e2f1 expression." (PMID 32462015, 2020). "The beneficial effects of 5-FdU on metastatic breast cancer cells appear to be dependent upon telomerase, as evidenced by the loss of therapeutic efficacy after genetic ablation or pharmacologic inhibition of TERT." (PMID 32071280, 2020). "However, no studies have evaluated the prevalence and prognostic significance of TERT promoter mutations in breast cancer." (PMID 29222734, 2018). "However, in breast cancer, the A allele of TERT rs2736098 shows a protective effect against breast cancer susceptibility in the Iranian population." (PMID 29695979, 2018). "In one large-scale cohort study, which include prognostic factors of breast cancer such as stage, age, subtype, grade, or other biomarkers with TERT promoter mutation, we will be able to investigate whether the TERT promoter mutation is a prognostic factor." (PMID 29222734, 2018). "However, to the best of our knowledge, no reports have evaluated the prevalence and prognostic significance of TERT promoter mutations in human breast cancer." (PMID 29222734, 2018).
breast carcinoma (continued). "Therefore, the present study aimed to provide information regarding TERT promoter mutations in samples from human breast cancer." (PMID 29222734, 2018). "However, a previous report identified two cases with TERT promoter mutations among eight human breast cancer cell lines (25%)." (PMID 29222734, 2018). "In conclusion, we have demonstrated the presence of TERT promoter mutation in breast cancer." (PMID 29222734, 2018). "We first compared the performance of PAFA, Eigen, CADD, GWAVA, FATHMM-MKL, and DANN on prioritizing coding variants from five well-studied genes (MLL2, CFTR, BRCA1, BRCA2, and TERT) associated with Kabuki syndrome, cystic fibrosis, breast cancer, or aggressive thyroid tumor, respectively." (PMID 29996888, 2018). "However, data suggested association between variants in TERT among women with a positive family history of breast cancer." (PMID 17848914, 2007). "Our findings suggested that variants in TERT could have an effect in individuals already at increased genetic risk of breast cancer, although the number of individuals with a family history of breast cancer was small." (PMID 17848914, 2007). "TERT Ex2-659G>A showed a borderline statistically significant association with a reduced risk of breast cancer in analysis of all cases and controls, which appeared to be stronger for individuals with a family history of breast cancer." (PMID 17848914, 2007). "However, a block 1 haplotype (ATCCA) in TERT was associated with protection from breast cancer when only individuals with a family history of breast cancer were studied (OR 0.61, 95% CI 0.38–0.97, P=0.034)." (PMID 17848914, 2007). "In addition, the TERT region was associated with ER− breast cancer." (PMID 27814745, 2016). "This SNP has been shown to interfere with an Ets2 binding site in the TERT promoter, and Xu and collaborators (2008) have shown that the minor genetic variant (the C-allele) inhibits c-Myc binding to the E-box consensus site that is present with the major T-variant allele in breast cancer cells." (PMID 26143636, 2015). "They only reported that, in the HER2 subtype, there was a correlation between TERT localization and breast cancer." (PMID 39871386, 2025). "Our series is the first to describe TERT focal amplification in breast metastatic setting and in a specific breast cancer subtype: ER + /HER2−." (PMID 39090361, 2024). "In human breast cancer cell PMC42, PKC-α is implicated in TERT phosphorylation, while protein phosphatase 2 A (PP2A) directly dephosphorylates TERT, affecting telomerase assembly and disrupting its activity on the contrary." (PMID 38278800, 2024). "Relative TERT mRNA expression levels were successfully quantified by qRT-PCR in primary tumor tissue samples of 106 breast cancer patients diagnosed between 1989 and 1993." (PMID 36768147, 2023). "As in breast tumors, mean TERT expression was higher in breast cancer cell lines with the rs10069690 CC genotype (n = 9) than in those with the CT/TT (n = 5 + 1) genotype (5.7–fold; p = 0.102, Kruskal-Wallis test of all three genotypes)." (PMID 36768147, 2023). "ER-positive breast cancer cell lines exhibited 2.8-fold higher mean TERT mRNA levels than ER-negative ones." (PMID 36768147, 2023). "Recent studies have identified HIF-1-dependent expression of PLXNB3, NARF, and TERT in hypoxic breast cancer cells." (PMID 37768037, 2023). "Recent studies have demonstrated that inhibition of PI3K/Akt pathway inhibits TERT expressions, which further diminishes proliferation of lung adenocarcinoma cells and breast cancer cells." (PMID 36938425, 2023).
breast carcinoma (continued). "Similar to normal cells, there was one outlier among the breast cancer cell lines, Hs 578T, which expressed TERT at ≈125–fold lower levels than the mean of the remaining 14 cell lines." (PMID 36768147, 2023). "The molecular mechanisms of telomerase reverse transcriptase (TERT) upregulation in breast cancer (BC) are complex." (PMID 35563554, 2022). "Cytoband 5p 14.3-12 contains TERT and gains in this cytoband have been asociated with this breast cancer and also with recurrence." (PMID 35885119, 2022). "STAT3 binding to the promoter in breast cancer stem cells along with STAT5 to the distal promoter region resulted in the activation of TERT expression and telomerase activity." (PMID 33802026, 2021). "To date, it has been shown that overexpression of β-TERT in breast cancer cells results in an anti-apoptotic chemoprotective phenotype, and overexpression of the ∆4–13 TERT variant in sarcoma cells induced proliferation via Wnt-signaling activation." (PMID 33924498, 2021). "In breast cancer, TERT can upregulate WNT signaling but only in a cell line dependent manner: out of four cell lines tested, only one showed WNT reporter activity in response to TERT overexpression." (PMID 34439356, 2021). "One patient with PTC and other two malignancies (sigmoid colon cancer diagnosed before TC and breast cancer diagnosed after TC), harboring TPM3/NTRK1 and TERT C228T mutations in PTC, underwent chemotherapy treatment and subsequently died." (PMID 33923728, 2021). "We next assessed the connection between the inverse expression patterns of SLX4IP and TERT and breast cancer patient outcomes, including progression to metastasis." (PMID 32071280, 2020). "Our data showing that FK506 decreases TERT expression are in line with previous publications showing similar effects of FK506 in breast cancer (MCF7) and immortalized T-cells (jurkat cell lines)." (PMID 32736525, 2020). "The SP1 transcription factor is linked to breast cancer and Huntington's disease, acting together with ATF7IP to maintain telomerase activity via inducing the expression of TERT and TERC." (PMID 32157780, 2020). "Taken together, these results reveal that SLX4IP and TERT are intricately related to one another in distinct human breast cancer subtypes, and this relationship presages metastatic progression and patient survival." (PMID 32071280, 2020). "To address this important question, we used a diverse array of primary breast cell and patient-derived tissue sources to evaluate the relationship between SLX4IP and TERT in human breast cancers." (PMID 32071280, 2020). "As shown in Addition file 10, the expression pattern of TERT in colon cancer is very different from that in breast cancer and lung cancer." (PMID 31856825, 2019). "Evaluation of SNPs from 3,677 women with TNBC and 4,708 controls supported the association of 25 known breast cancer susceptibility loci, including 2q35, LGR6, MDM4, TERT, ESR1, TOX3, and 19p13.1 with TNBC." (PMID 31379942, 2019). "Many malignant tumor cells have TERT expression or telomerase activity, with > 90% of breast cancer cases having telomerase activity." (PMID 29222734, 2018). "A concomitant upregulation of TERT and MYC identified patients with a high risk of breast cancer recurrence." (PMID 29100407, 2017). "Increased TERT gene dosage was seen in about 30% of various human tumor-derived cell lines, including breast cancer cells." (PMID 29100407, 2017). "Silencing of ETS2 results in a reduction of TERT gene expression leading to increased human breast cancer cell death, while reconstitution with recombinant TERT reverses that effect." (PMID 28184371, 2017). "The most highly mutated DHS in breast cancers is at chr5:1325957-1328153, located within an intron of CLPTM1L and 30 kb upstream of TERT." (PMID 28874753, 2017). "We here investigated the effects of three previously reported functional polymorphisms in the TERT and TERC genes 37, 38, 39, 40 on TL and breast cancer risk." (PMID 28707432, 2017).